CYB5R3 (cytochrome b5 reductase 3)
Description:
Catalyzes the reduction of two molecules of cytochrome b5 using NADH as the electron donor.
Synonyms: B5R; DIA1
Tractability: Small molecule: a structure with a bound ligand is known. Antibody: its Gene Ontology location is reachable by antibodies, with high confidence. PROTAC: ubiquitination databases record sites on it; its protein half-life has been measured.
Target class: Enzyme; Oxidoreductase
Gene: Protein-coding gene on chromosome 22 (42,615,730 to 42,720,870, reverse strand). Ensembl gene ENSG00000100243.
Subcellular location: Endoplasmic reticulum membrane (Isoform 1); Mitochondrion outer membrane; Cytoplasm (Isoform 2)
Subcellular location (Human Protein Atlas): Endoplasmic reticulum; Calyx; Connecting piece; Mid piece; Perinuclear theca; Principal piece
Pathways (Reactome):
Metabolism: Phase I - Functionalization of compounds; Vitamin C (ascorbate) metabolism
Immune System: Neutrophil degranulation
Gene Ontology:
Molecular function: cytochrome-b5 reductase activity, acting on NAD(P)H; cytochrome-b5 reductase activity, acting on NADH; FAD binding; nitrite reductase (NO-forming) activity; protein binding; oxidoreductase activity
Biological process: nitric oxide biosynthetic process; blood circulation
Cellular component: cytoplasm; endoplasmic reticulum; endoplasmic reticulum membrane; lipid droplet; membrane; mitochondrial membrane; mitochondrion; nitric-oxide synthase complex; azurophil granule lumen; extracellular region; hemoglobin complex; mitochondrial outer membrane
Genetic constraint (gnomAD): Loss-of-function variants: 27 observed, 34.69 expected, observed/expected ratio (o/e) 0.78, 90% interval 0.57 to 1.07. The upper end of that interval is the gene's LOEUF score, 1.07, which puts it in group 4 of 6, group 1 being the genes least tolerant of losing a copy. Missense variants: 459 observed, 403.52 expected, observed/expected ratio (o/e) 1.14, 90% interval 1.05 to 1.23. Synonymous variants: 177 observed, 157.34 expected, observed/expected ratio (o/e) 1.12, 90% interval 1 to 1.27.
Gene-disease validity (ClinGen):
ClinGen rates the evidence that CYB5R3 causes each of these diseases.
methemoglobinemia due to deficiency of methemoglobin reductase (autosomal recessive): Definitive.
Homologues: Orthologues: chimpanzee CYB5R3 (95% identical), dog CYB5R3 (93% identical), pig CYB5R3 (92% identical), guinea pig CYB5R3 (88% identical), mouse Cyb5r3 (87% identical), rat Cyb5r3 (86% identical), macaque CYB5R3 (82% identical), rabbit CYB5R3 (76% identical), zebrafish cyb5r3 (71% identical), tropical clawed frog cyb5r3 (70% identical), Drosophila melanogaster CG5946 (57% identical), Caenorhabditis elegans T05H4.4 (55% identical), and 1 more. Paralogues in human: CYB5R1 (60% identical), CYB5R2 (54% identical), CYB5R4 (28% identical), CYB5RL (26% identical), OXNAD1 (18% identical).
Diseases named in the same sentence as CYB5R3 in open-access papers:
CYB5R3 is named in the same sentence as 53 diseases in open-access papers, as found by Europe PMC text mining. Sharing a sentence is not in itself a finding about the gene and the disease. The quoted sentences say what the papers report.
methemoglobinemia (7 papers, 2017 to 2025). An inherited or acquired condition characterized by abnormally increased levels of methemoglobin in the blood. "Recessive congenital methemoglobinemia is caused by mutations in the CYB5R3 gene, which encodes NADH-CYB5R3." (PMID 40429944, 2025). "Naturally occurring CYB5R3 deficiency causing methemoglobinemia (equivalent to type I RCM in humans) has also been reported in dogs (Online Mendelian Inheritance in Animals [OMIA] #002131-9615,) and cats (OMIA #002131-9685; #01171-9685,)." (PMID 37048064, 2023). "In humans, erythrocytic CYB5R3 deficiency is characterized by cyanosis and mild clinical signs and referred to as type I recessive congenital methemoglobinemia (type I RCM; Online Mendelian Inheritance in Man [OMIM] #250800)." (PMID 37048064, 2023). "In contrast, type II RCM, characterized by the complete or almost complete loss of activity of the CYB5R3 enzymes leads to devastating developmental and neurological disease in humans, likely due to fatty acid disturbances besides methemoglobinemia." (PMID 37048064, 2023). "Two novel missense variants in addition to two previously reported variants in the CYB5R3 gene were identified among 30 dogs with persistent methemoglobinemia due to CYB5R deficiency." (PMID 33293645, 2020). "NADH-cytochrome b5 reductase 3 was downregulated in rats exposed to fast decompression, and defects in this protein has been associated with methemoglobinemia and tissue hypoxia." (PMID 28977037, 2017). "Pathogenic variants in the CYB5R3 enzyme cause two types of methemoglobinemia." (PMID 36837579, 2023). "Under normal conditions, the CYB5R3 enzyme in erythrocytes converts the methemoglobin to its ferrous state (Fe++); however, due to genetic mutations in the CYB5R3 gene, it cannot be converted back into ferrous state (Fe++) from ferric (Fe+++) state, resulting in methemoglobinemia." (PMID 36837579, 2023). "We conclude that CYB5R3 deficiency is the predominate cause of canine hereditary methemoglobinemia." (PMID 33293645, 2020). "This prospective study had two objectives: firstly, to characterize the molecular basis and clinical spectrum in a cohort of dogs with hereditary methemoglobinemia; and secondly, to determine if there are biochemical or clinical phenotypic differences ascribed to separate CYB5R3 gene variants." (PMID 33293645, 2020). "Methemoglobin does not bind oxygen and must be reduced back to its ferrous state by cytochrome b5 reductase 3 (CYB5R3) to prevent methemoglobinemia, a life-threatening condition." (PMID 38432636, 2024). "Background and Objective: Mutations in the CYB5R3 gene cause reduced NADH-dependent cytochrome b5 reductase enzyme function and consequently lead to recessive congenital methemoglobinemia (RCM)." (PMID 36837579, 2023). "Pyknocytosis and eccentrocytosis observed in horses with methemoglobinemia caused by FAD deficiency was never reported in cats or dogs with reduced erythrocytic CYB5R3 activity." (PMID 37048064, 2023).
breast carcinoma (6 papers, 2020 to 2023). "Several research groups demonstrated that CYB5R3 overexpression and polymorphisms increase the risk of breast cancer in women, especially women of African ancestry." (PMID 36441026, 2022). "Two groups have reported that membrane-bound Cyb5R3 overexpression and polymorphism are associated with breast cancer risk in women." (PMID 32411317, 2020). "Interestingly, the same study showed that CYB5R3 deficiency was deleterious in breast cancer, as evidenced by increased tumor colonization and metastasis." (PMID 36441026, 2022). "CYB5R3 (identified as UOB-COL-4 in our study) has been shown to be downregulated in breast cancer, negating its ability to detoxify the responsive hydroxylamine metabolites of known mammary carcinogens." (PMID 36008952, 2022). "In addition, CYB5R3 is believed to be an oncogene, and its overexpression is intertwined with poor prognosis in breast cancer and hepatocellular carcinoma." (PMID 38074856, 2023). "Cyb5R3 is overexpressed in breast cancer and correlate with poor disease-free and overall survival." (PMID 34065197, 2021).
lung carcinoma (3 papers, 2022 to 2025). "The research discovered that CYB5R3 presence is reduced in lung cancer and that an increase in CYB5R3 can cause cancer cells to die." (PMID 38253797, 2024). "To confirm the tumor-suppressive role of CYB5R3 in human lung cancer cells, we investigated the effects of CYB5R3 overexpression using Ad-CYB5R3, an adenovirus that expresses CYB5R3." (PMID 38253797, 2024). "Our findings highlight the importance of CYB5R3 as a tumor suppressor for the development of CYB5R3-based therapeutics for lung cancer." (PMID 38253797, 2024). "Here, we showed that overexpression of CYB5R3 induces apoptosis in lung cancer cells in vitro and in vivo." (PMID 38253797, 2024). "To examine the expression pattern of CYB5R3 in human lung cancer cells, we measured CYB5R3 mRNA levels using quantitative RT‒PCR in two human lung fibroblast lines and eight NSCLC cell lines." (PMID 38253797, 2024). "Transcriptome analysis revealed that apoptosis- and endoplasmic reticulum (ER) stress-related genes are upregulated in CYB5R3-overexpressing lung cancer cells." (PMID 38253797, 2024). "Our findings suggest that CYB5R3 functions as a tumor suppressor and can be utilized in the development of anti-lung cancer drugs." (PMID 38253797, 2024). "We also found that 91% (29 of 32) of the normal lung tissues exhibited high CYB5R3 expression, while only 19% (24 of 128) of the lung cancer tissues showed high CYB5R3 expression, indicating that CYB5R3 expression is associated with lung carcinogenesis." (PMID 38253797, 2024). "As expected, CYB5R3 decreased the GSH/GSSG ratio and increased NOX4-dependent H2O2 production, and treatment with cell-permeable GSH-EE attenuated apoptosis mediated by CYB5R3 overexpression in lung cancer cells." (PMID 38253797, 2024). "CYB5R3 overexpression induces apoptosis in lung cancer cells via ER stress and ROS generation, suggesting approaches for the development of CYB5R3-based therapeutics for lung cancer." (PMID 38253797, 2024). "Here, we show that CYB5R3 expression is downregulated in human lung cancer cell lines and tissues." (PMID 38253797, 2024). "Accumulated data on CYB5R3 have provided evidence that CYB5R3 inhibits lung cancer growth." (PMID 38253797, 2024). "In addition, the in vivo study in the CYB5R3 KO mouse model revealed the tumor-suppressive function of CYB5R3 in lung cancer." (PMID 38253797, 2024). "In this study, we provide evidence that CYB5R3 overexpression induces ER stress by promoting ADP-ribosylation of PERK and IRE1α, resulting in apoptosis in lung cancer cells." (PMID 38253797, 2024). "Consistent with the analysis of public data, IHC analysis revealed that CYB5R3 expression in lung cancer tissues was lower than that in normal tissues." (PMID 38253797, 2024). "Genetic knockdown of CYB5R3 in lung cancer cells revealed slow proliferation and metastasis but did not affect cancer cell survival, pointing to a potential link between CYB5R3 and lung cancer." (PMID 36441026, 2022).
ovarian carcinoma (3 papers, 2016 to 2021). A malignant neoplasm originating from the surface ovarian epithelium. "The low expression of FBXO21, ANP32E, and CYB5R3 was significantly associated with longer recurrence-free survival time of ovarian cancer." (PMID 34660776, 2021). "Combining TCGA ovarian cancer dataset, we identified differentially expressed marker genes that were significantly associated with prognosis of ovarian cancer, including ANP32E, STAT1, GPRC5A, EGFL6, PMP22, FBXO21, and CYB5R3." (PMID 34660776, 2021). "In summary, altered ABHD2, ELAC2 and CYB5R3 mRNA expression was identified through our functional genomics screen and was significantly reduced in ovarian cancer, especially in HGSOC, relative to that in SBT or normal ovarian epithelium." (PMID 27323405, 2016). "Like ABHD2, ELAC2 and CYB5R3 mRNA levels were significantly lower in ovarian cancer than in SBT (p=0.008 and 0.003, respectively)." (PMID 27323405, 2016). "Furthermore, PMP22, FBXO21, and CYB5R3 expression was significantly lower in ovarian cancer tissues compared with normal tissues." (PMID 34660776, 2021). "Our predicted ovarian specific biomarker CYB5R3 is reported to be involved in ovarian cancer." (PMID 29971090, 2018). "Furthermore, marker genes, STAT1, ANP32E, GPRC5A, and EGFL6, were highly expressed in ovarian cancer, while PMP22, FBXO21, and CYB5R3 were lowly expressed in ovarian cancer." (PMID 34660776, 2021). "Furthermore, there is no report concerning the expression and role of FBXO21 and CYB5R3 in ovarian cancer." (PMID 34660776, 2021). "Comparing histologic subtypes of epithelial ovarian cancers, ELAC2 and CYB5R3 mRNA levels were significantly lower in HGSOC than in non-HGSOC (p<0.0001, p=0.03, respectively)." (PMID 27323405, 2016).
atherosclerosis (2 papers, 2023 to 2024). A disease characterized by the build-up of fatty material and calcium deposition in the arterial wall resulting in partial or complete occlusion of the arterial lumen. "Based on our findings, we suggest here that APOO may influence plasma cholesterol levels and atherosclerosis through NRF2/CYB5R3-mediated regulation of biliary and fecal cholesterol excretion." (PMID 38830896, 2024).
autosomal recessive congenital methemoglobinemia (2 papers, 2022 to 2023). "NADH-cytochrome b5 reductase 3 deficiency is an important genetic cause of autosomal recessive congenital methemoglobinemia (RCM)." (PMID 36837579, 2023). "Among the CYB5R genetic variants, CYB5R3 is well-characterized and deficiency in expression and activity is associated with type II methemoglobinemia, cancer, neurodegenerative disorders, diabetes, and cardiovascular disease." (PMID 36441026, 2022).
heart failure (2 papers, 2024 to 2025). Inability of the heart to pump blood at an adequate rate to meet tissue metabolic requirements. "There is no direct evidence linking the Cyb5a gene to heart failure although it does act as an electron carrier for Cyb5r3 a known contributor to heart failure and so presumably it is linked to heart failure through a similar pathway." (PMID 41446135, 2025).
lipid metabolism disorder (2 papers, 2018 to 2021). "Based on the new molecular and cellular functions discovered for CYB5R3 linked to the plasma membrane and mitochondria, the conventional conception that the cause of type II RHM is a lipid metabolism disorder should be revised." (PMID 30309019, 2018). "Moreover, KLF10-silenced groups exhibited overexpression of Cyb5r3, Fads1, and Fads2, which are involved in diseases such as lipid metabolism disorder." (PMID 34869587, 2021).
liver cancer (2 papers, 2016 to 2024). An epithelial or non-epithelial malignant neoplasm that arises from the liver. "We demonstrated that CYB5R3 overexpression also confers partial protection against xenobiotic-induced liver cancer in laboratory mice." (PMID 28721264, 2016). "However, another study demonstrated that CYB5R3 overexpression protected against chemically induced liver cancer in CYB5R3 transgenic mice." (PMID 38253797, 2024).
microcephaly (2 papers, 2022 to 2025). A congenital or acquired developmental disorder in which the circumference of the head is smaller than normal for the person's age and sex. "Deficiency in CYB5R3 UFMylation has been linked to microcephaly in mice, highlighting its significance in brain development." (PMID 39757643, 2025). "Mutations in CYB5R3 have been associated with congenital methemoglobinemia type II, a condition linked to microcephaly." (PMID 39757643, 2025). "Insufficient UFL1 and UFBP1 levels resulted in UFMylation defects in CYB5R3, thereby promoting microcephaly." (PMID 39757643, 2025). "Mutations of CYB5R3 and genes involved in the UFM1 system cause hereditary developmental disorders, and ufmylation-defective Cyb5r3 knock-in mice exhibit microcephaly." (PMID 36543799, 2022).
Alzheimer disease (1 paper, 2022). A progressive, neurodegenerative disease characterized by loss of function and death of nerve cells in several areas of the brain leading to loss of cognitive function such as memory and language. "It is possible that Alzheimer’s disease etiology involves a causal effect for loss of CYB5R3 in mitochondrial dysfunction; however, more studies in the neural system must be performed to establish such a relationship." (PMID 36441026, 2022). "CYB5R3 has also been implicated in neurodegenerative disorders, such as Alzheimer’s disease." (PMID 36441026, 2022).
amyloidosis (1 paper, 2020). A disorder characterized by the localized or diffuse accumulation of amyloid protein in various anatomic sites. "We also profiled CSF in the 5xFAD mouse model to validate amyloidosis-induced changes, and found consistent mitochondrial decreases (SOD2, PRDX3, ALDH6A1, ETFB, HADHA, and CYB5R3) in both human and mouse samples." (PMID 32711556, 2020).
cardiac arrest (1 paper, 2022). Cessation of breathing and/or cardiac function. "At 5 days after tamoxifen injection, we observed severe bradycardia, leading to cardiac arrest in ac-CYB5R3–KO mice in contrast with ac-WTs." (PMID 36106636, 2022).
cardiac hypertrophy (1 paper, 2022). "To determine whether cardiac hypertrophy and HF cause changes in CYB5R3 expression, we subjected C57BL6/J male mice to transverse aortic constriction (TAC)." (PMID 36106636, 2022). "Using a conditional cardiomyocyte-specific CYB5R3-knockout mouse, we discovered that deletion of CYB5R3 in male, but not female, adult cardiomyocytes causes cardiac hypertrophy, bradycardia, and SCD." (PMID 36106636, 2022).
clear cell renal cell carcinoma (1 paper, 2024). "In clear cell renal cell carcinoma, HADHA overexpression inhibits tumor growth by increasing the expression of CYB5R3 or ACAT1." (PMID 38253797, 2024).
congenital methemoglobinemia (1 paper, 2022). "CYB5R3 is known to cause recessive congenital methemoglobinemia (RCM) types I and II39." (PMID 36543799, 2022).
Encephalopathy (1 paper, 2018). Encephalopathy is a term that means brain disease, damage, or malfunction. "The membrane-bound CYB5R3 isoform is anchored to the outer mitochondrial membrane (OMM), endoplasmic reticulum (ER), and plasma membrane (PM) of all cells, and its deficiency, causes type II RHM, an incurable encephalopathy with permanent mild cyanosis." (PMID 30309019, 2018).
endothelial dysfunction (1 paper, 2020). In vascular diseases, endothelial dysfunction is a systemic pathological state of the endothelium (the inner lining of blood vessels) and can be broadly defined as an imbalance between vasodilating and vasoconstricting substances produced by (or acting on) the endothelium. "PKA signaling and Cyb5r3 level is upregulated, likely serving as a self-protective mechanism to maintain endothelial function and vasodilation against I/R injury, while eNOS signaling is downregulated as an indication of endothelial dysfunction." (PMID 32867129, 2020).
esophageal cancer (1 paper, 2023). A primary or metastatic malignant neoplasm involving the esophagus. "qRT-PCR detection demonstrated increased expression of MPC1, COX6C, CYB5R3, CASP7, and CYCS in esophageal cancer patients." (PMID 38196829, 2023). "Our results showed that the levels of MPC, COX6C, CYB5R3, CASP7, and CYCS were significantly upregulated in tumor tissues compared with adjacent non-tumor tissues in esophageal cancer patients." (PMID 38196829, 2023). "In addition, we found by qRT-PCR that the levels of MPC1, COX6C, CYB5R3, CASP7, and CYCS in tumor tissues of esophageal cancer patients were significantly higher than adjacent non-tumor tissues, suggesting that these genes may have some value in clinical diagnosis and prognosis." (PMID 38196829, 2023).
follicular adenomas (1 paper, 2021). "Furthermore, increased Cyb5R3 activity is observed in papillary thyroid cancer compared to follicular adenomas." (PMID 34065197, 2021).
Glucose intolerance (1 paper, 2024). Glucose intolerance (GI) can be defined as dysglycemia that comprises both prediabetes and diabetes. "Cyb5r3 knockout mice show more pronounced β-cell dedifferentiation and glucose intolerance after chronic SU administration, high-fat diet feeding, and during aging." (PMID 38335173, 2024).
lung adenocarcinoma (1 paper, 2024). A carcinoma that arises from the lung and is characterized by the presence of malignant glandular epithelial cells. "CYB5R3 expression was downregulated in both lung adenocarcinoma (LUAD) and lung squamous cell carcinoma (LUSC)." (PMID 38253797, 2024). "In particular, geranylgeranyl diphosphate synthase (GGPPS), which is involved in CYB5R3 prenylation, is overexpressed in lung adenocarcinoma." (PMID 38253797, 2024).